OR4N5 (olfactory receptor family 4 subfamily N member 5)
Description:
Odorant receptor.
Tractability: Antibody: UniProt places it where antibodies can reach, with medium confidence; UniProt predicts a signal peptide or a membrane-spanning region; its Gene Ontology location is reachable by antibodies, with medium confidence.
Gene: Protein-coding gene on chromosome 14 (20,138,820 to 20,145,471, forward strand). Ensembl gene ENSG00000184394.
Subcellular location: Cell membrane
Pathways (Reactome):
Sensory Perception: Expression and translocation of olfactory receptors
Gene Ontology:
Molecular function: olfactory receptor activity; G protein-coupled receptor activity
Biological process: detection of chemical stimulus involved in sensory perception of smell; G protein-coupled receptor signaling pathway
Cellular component: plasma membrane; membrane
Genetic constraint (gnomAD): Missense variants: 425 observed, 385.15 expected, observed/expected ratio (o/e) 1.1, 90% interval 1.02 to 1.2. Synonymous variants: 155 observed, 147.54 expected, observed/expected ratio (o/e) 1.05, 90% interval 0.92 to 1.2.
Homologues: Orthologues: chimpanzee OR4N5 (98% identical), macaque OR4N5 (91% identical), dog OR4N5 (89% identical), guinea pig OR4N5 (87% identical), rabbit OR4N5 (87% identical), rat Or4n5 (87% identical), mouse Or4n5 (86% identical). Paralogues in human: OR4N2 (84% identical), OR4N4 (84% identical), OR4N4C (84% identical), OR4M1 (58% identical), OR4M2B (57% identical), OR4M2 (57% identical), OR4D1 (52% identical), OR4D5 (51% identical), OR4D11 (51% identical), OR4D9 (50% identical), OR4E2 (50% identical), OR4D10 (50% identical), and 116 more.
Diseases named in the same sentence as OR4N5 in open-access papers:
OR4N5 is named in the same sentence as 1 disease in open-access papers, as found by Europe PMC text mining. Sharing a sentence is not in itself a finding about the gene and the disease. The quoted sentences say what the papers report.
breast carcinoma (1 paper, 2024). "According to information from the KEGG database, we have discovered that in breast cancer, olfactory receptors such as OR11H6, OR1J4, OR4N5, and OR11G2O are associated with the olfactory transduction pathway." (PMID 38254021, 2024).